SOX5 (SRY-box transcription factor 5)
Description:
Transcription factor involved in chondrocytes differentiation and cartilage formation. Specifically binds the 5'-AACAAT-3' DNA motif present in enhancers and super-enhancers and promotes expression of genes important for chondrogenesis, including cartilage matrix protein-coding genes, such as COL2A1 and AGC1. Required for overt chondrogenesis when condensed prechondrocytes differentiate into early stage chondrocytes: SOX5 and SOX6 cooperatively bind with SOX9 on active enhancers and super-enhancers associated with cartilage-specific genes, and thereby potentiate SOX9's ability to transactivate. Not involved in precartilaginous condensation, the first step in chondrogenesis, during which skeletal progenitors differentiate into prechondrocytes. Together with SOX6, required to form and maintain a pool of highly proliferating chondroblasts between epiphyses and metaphyses, to form columnar chondroblasts, delay chondrocyte prehypertrophy but promote hypertrophy, and to delay terminal differentiation of chondrocytes on contact with ossification fronts. Binds to the proximal promoter region of the myelin protein MPZ gene.
Synonyms: L-SOX5; MGC35153; L-SOX5B; L-SOX5F; LAMSHF
Tractability: PROTAC: ubiquitination databases record sites on it.
Gene: Protein-coding gene on chromosome 12 (23,529,504 to 24,562,544, reverse strand). Ensembl gene ENSG00000134532.
Subcellular location: Nucleus
Subcellular location (Human Protein Atlas): Nucleoplasm
Gene Ontology:
Molecular function: protein binding; transcription cis-regulatory region binding; DNA-binding transcription factor activity; DNA-binding transcription factor activity, RNA polymerase II-specific; RNA polymerase II cis-regulatory region sequence-specific DNA binding; cis-regulatory region sequence-specific DNA binding
Biological process: asymmetric neuroblast division; cellular response to transforming growth factor beta stimulus; positive regulation of cartilage development; positive regulation of chondrocyte differentiation; positive regulation of mesenchymal stem cell differentiation; cartilage condensation; cartilage development; cell fate commitment; chondrocyte differentiation; regulation of transcription by RNA polymerase II; transcription by RNA polymerase II
Cellular component: nucleoplasm; chromatin; nucleus
Genetic constraint (gnomAD): Loss-of-function variants: 8 observed, 70.8 expected, observed/expected ratio (o/e) 0.11, 90% interval 0.065 to 0.2. The upper end of that interval is the gene's LOEUF score, 0.2, which puts it in group 1 of 6, group 1 being the genes least tolerant of losing a copy. Missense variants: 560 observed, 867.1 expected, observed/expected ratio (o/e) 0.65, 90% interval 0.6 to 0.69. Synonymous variants: 311 observed, 313.08 expected, observed/expected ratio (o/e) 0.99, 90% interval 0.9 to 1.09.
Gene-disease validity (ClinGen):
ClinGen rates the evidence that SOX5 causes each of these diseases.
Lamb-Shaffer syndrome (autosomal dominant): Definitive.
Homologues: Orthologues: macaque SOX5 (100% identical), pig SOX5 (99% identical), guinea pig SOX5 (99% identical), dog SOX5 (99% identical), chimpanzee SOX5 (99% identical), mouse Sox5 (97% identical), rat Sox5 (97% identical), rabbit SOX5 (94% identical), tropical clawed frog sox5 (87% identical), zebrafish sox5 (75% identical), Drosophila melanogaster Sox102F (23% identical), Caenorhabditis elegans egl-13 (21% identical), and 2 more. Paralogues in human: SOX6 (61% identical), SOX13 (37% identical), SOX30 (14% identical), CFAP65 (13% identical), SOX9 (12% identical), SOX8 (11% identical), SOX18 (10% identical), SOX10 (10% identical), SOX1 (10% identical), SOX17 (10% identical), SOX11 (10% identical), SOX4 (10% identical), and 8 more.
Diseases named in the same sentence as SOX5 in open-access papers:
SOX5 is named in the same sentence as 132 diseases in open-access papers, as found by Europe PMC text mining. Sharing a sentence is not in itself a finding about the gene and the disease. The quoted sentences say what the papers report.
glioma (17 papers, 2008 to 2024). A benign or malignant brain and spinal cord tumor that arises from glial cells (astrocytes, oligodendrocytes, ependymal cells). "SOX5, a member of the high-mobility group, inhibits dermal glioma formation in mice with ink4a deficiency by induction of acute cellular senescence." (PMID 36465363, 2022). "In addition, high SOX5 expression has been found to be associated with poor prognosis and tumor metastasis in cancers such as lung adenocarcinoma, glioma, and nasopharyngeal carcinoma." (PMID 38835366, 2024). "Thus in neuronal progenitor cells high SOX5 expression is associated with a premature cell cycle exit and in human glioma cells with a poor proliferative capacity." (PMID 24945754, 2014). "The next cascade in this complex mechanism involved SOX5, upregulated in glioma, as a downstream target of miR-195." (PMID 37047365, 2023). "The overexpression of SOX5 in human glioma cells led to a reduction in clone formation and an inhibition of proliferation." (PMID 37047365, 2023). "Overexpression of SOX5 has been shown to inhibit proliferation in both in vitro experiments of human glioma cell lines and in vivo experiments using platelet-derived growth factor β (PDGFβ)-induced glioma in mice." (PMID 34012965, 2021). "For example, SOX5 could inhibit glioma proliferation in vitro, while SOX5 knockdown elevates the ability of glioma growth in mouse models." (PMID 38561355, 2024). "In addition, high expression of SOX5 was negatively correlated with the survival rate of glioma patients." (PMID 38835366, 2024). "SOX5 can suppress PDGFB (platelet-derived growth factor B)-induced glioma development in mice by inhibiting cell proliferation and inducing acute cellular senescence through the regulation of p27Kip1 (cyclin-dependent kinase inhibitor 1B) and AKT1 (AKT serine-threonine protein kinase)." (PMID 37047365, 2023). "In a mouse model, SOX5 inhibits glioma formation by inducing acute cellular senescence." (PMID 36761024, 2023). "Interestingly, SOX5 expression is lower in both glioma samples and glioma cell lines than in normal adult brain." (PMID 34012965, 2021). "In addition, SOX5 was found to regulate the malignant progression of glioma cells via direct binding to the promoter of its downstream target gene Gelsolin, and the promoter of SNHG12." (PMID 31620362, 2019). "Similarly, SNHG12 could upregulate SOX5 expression and exert oncogenic functions in glioma cells, while SOX5 increases SNHG12 expression by activating its promoter." (PMID 31186064, 2019). "MiR-101-3p and miR-195 were found to be putative targets of SNHG12, which inhibited the progression of glioma by down-regulating their target genes, Forkhead Box Protein P1 (FOXP1), and Sry-Box 5 (SOX5)." (PMID 31620362, 2019). "In the TDP43/SNHG12/miR-195/SOX5 pathway of glioma cells, SOX5 promotes the transcription of SNHG12 and forms a positive feedback loop to regulate the biological behavior of glioma cells." (PMID 30736838, 2019). "Both of them are overexpressed in gliomas, and while SOX6 was recently proposed as a possible important factor in obesity-related insulin resistance, SOX5 overexpression and amplification has been observed in human testicular seminoma." (PMID 18510758, 2008). "SOX5 was over-expressed in GBM tissues, SNHG12-miR-195-SOX5 feedback loop could regulate the glioma cells’ malignant progression." (PMID 32388501, 2020). "Taken together, these findings suggest that SNHG12 acts as a key player in the progression of glioma by its involvement in the miR-101-3p/FOXP1 axis, and the miR-195/SOX5 axis, which are stabilized by the binding of the RNA-binding proteins, HuR and TDP43, respectively." (PMID 31620362, 2019). "In glioma, NEAT1 could specifically bind to miR-449b-5p and miR-181d-5p to inhibit their transcriptions, leading to the over-expression of oncogenes c-Met and SOX5, respectively." (PMID 30053878, 2018).
glioma (continued). "SOX5 binds to the promoter regions of ZO-1 (Zonula Occludens-1), occluding, and claudin-5 and regulates the expression of tight junction proteins in GECs, thus controlling the permeability of the blood–tumor barrier (BTB), the limiting factor for drug delivery in glioma treatments." (PMID 37047365, 2023).
breast cancer (15 papers, 2015 to 2025). A primary or metastatic malignant neoplasm involving the breast. "In breast cancer, SOX5 is highly expressed in breast cancer tissues compared with adjacent healthy tissues, and overexpression of SOX5 is associated with decreased overall survival of breast cancer patients." (PMID 38835366, 2024). "SOX5 has been linked to breast cancer, gastric cancer, colorectal cancer, lung cancer, and osteosarcoma." (PMID 35880568, 2022). "In addition, a recent study also found that Sox5 expression is associated with bone metastasis of breast cancer." (PMID 38835366, 2024). "Furthermore, SOX5 has been linked to physiological and pathological processes in a variety of cancers, including breast cancer, gastric cancer, lung cancer, ovarian cancer, colorectal cancer, and hepatocellular carcinoma." (PMID 35880568, 2022). "For example, mutations affecting SOX5 and TP53BP1 can both promote proliferation in breast cancers through very different mechanisms." (PMID 39975330, 2025). "TBXT promotes bone metastasis in breast cancer by transcriptionally activating oncogene SRY-Box transcription factor 5 (SOX5)." (PMID 38965548, 2024). "Existing experiments have shown that SOX5 is highly expressed in many malignant tumors, including prostate cancer, breast cancer, hepatocellular carcinoma, nasopharyngeal carcinoma and other malignant tumors." (PMID 38835366, 2024). "CircDOCK1 (circ_0020394) promotes the progression of breast cancer via regulating the miR-132-3p/Sox5 pathway." (PMID 38570856, 2024). "At the same time, SOX5, which is highly expressed in many cancers such as prostate cancer, bladder cancer, liver cancer and breast cancer, can also promote the progression of cancer and the proliferation, migration and invasion of cancer cells." (PMID 38835366, 2024). "In patients with breast cancer, SOX5 binds to the promoter of TWIST1 (a significant regulator of embryonic morphogenesis), thereby promoting its expression and facilitating EMT for metastasis." (PMID 38965548, 2024). "SOX5 can positively modulate the expression of enhancer of zeste homologue 2 (EZH2) in the context of breast cancer." (PMID 35468879, 2022). "Besides this, ID4, SEMA3F, FOXD, KCNK5, WNK4 and ECM1 associate with chemoresistance origin and SOX5, ITM2A, SNCG, EPHA4, NTS, FGFR2 and ENPEP associate moreover with breast cancer tumorigenesis." (PMID 37239828, 2023). "SOX5 is significantly regulated in breast cancer (BC) cell lines, and promoted progress of BC cells." (PMID 37531195, 2023). "The positive targeting relationship between SOX5 and EZH2 has been previously identified in breast cancer." (PMID 35468879, 2022). "Notably, SOX5, an EMT inducer through activation of TWIST1 in breast cancer cells, was downregulated in LN + cases." (PMID 29074988, 2017). "Barx2 increased expression of both ESR1 isoforms, the estrogen-responsive genes (SOX5, RBM15 and Dynein), the tissue inhibitor of metalloproteinase (TIMP) genes (TIMP1 and TIMP3), and MMP-9, all of which promote breast cancer cell growth, survival, and invasion." (PMID 27533254, 2016).
Intellectual disability (14 papers, 2017 to 2026). "Presently, the majority of intellectual disabilities and bone developmental disorders associated with SOX5 are dominant disorders resulting from haploinsufficiency." (PMID 39905544, 2025). "We confirmed that the SOX5 p.Thr74Met variant is associated with intellectual disability in a second-generation Chinese family." (PMID 39905544, 2025). "A previously identified missense variant (c.221C > T) in the SOX5 gene was determined to be the underlying cause of intellectual disability in a Chinese family." (PMID 39905544, 2025). "In a Chinese family presenting with intellectual disability, we identified a missense variant (c.221C > T, p.Thr74Met) in the SOX5 gene." (PMID 39905544, 2025). "This study extends the clinical and genetic spectrum associated with LAMSHF and consolidates evidence that SOX5 gene mutations lead to variable degrees of intellectual disability, language delay, and other clinical features." (PMID 39075495, 2024). "Whereas AUTS2 and SOX5 have been linked to predisposition to neurological conditions such as autism spectrum disorder, intellectual disability, and neurodevelopmental disorder." (PMID 39535534, 2024). "Knowledge of the underlying mechanisms may offer valuable insights for the development of novel therapeutic strategies for patients with intellectual disabilities associated with SOX5 variants." (PMID 39905544, 2025). "This study reports on a Chinese family with a SOX5 variant associated with intellectual disability." (PMID 39905544, 2025). "SOX5 is associated with neuronal development, intellectual disability, and autism." (PMID 31623237, 2019). "Finally, human Sox5 has been implicated in a number of diseases and intellectual disability in humans." (PMID 30190506, 2018). "Finally, in the search for novel molecular factors underlying intellectual disability, a 2016 large-scale trio-based whole-exome study discovered significantly more SOX5 loss-of-function coding mutations than expected among ~2,100 affected individuals." (PMID 29214085, 2017). "In this study, we examined the SOX5 variant (c.221C > T, p.Thr74Met) within a Chinese family presenting with intellectual disability and evaluated the functional implications of SOX5 by in vitro experiment." (PMID 39905544, 2025). "And the reported patients with haploinsufficiency of the SOX5 gene had common features included developmental delay, intellectual disability, speech delay and dysmorphisms such as strabismus, frontal bossing, ear abnormalities, and low nasal bridge." (PMID 39075495, 2024). "These patients were reported to have intellectual disability with additional features of language delay, facial dysmorphic signs, and behavior deficits, consistent with the previously delineated SOX5 haploinsufficiency phenotype." (PMID 29214085, 2017). "We reported a 7-year-old boy with severe intellectual disability, seizures, autism, strabismus, and myopia, who carries a novel SOX5 gene variant (c.1769T > C, p.Leu590Ser) inherited from his mother, who has a milder phenotype." (PMID 40500800, 2025). "In contrast, his mother, who carried the identical SOX5 variant, displayed only mild intellectual disability, strabismus, and myopia, with no signs of epilepsy or autism." (PMID 40500800, 2025). "We report a child with de novo SOX5-related Lamb-Shaffer syndrome, ASD, ADHD, and queried intellectual disability who developed a paradoxical reaction to very low-dose risperidone, followed by clinical stabilization and improvement upon shifting to aripiprazole." (PMID 41531626, 2025). "This case describes a child with de novo SOX5-related Lamb-Shaffer syndrome, ASD, ADHD, and query intellectual disability who developed paradoxical behavioral activation after initiation of very low-dose risperidone, with resolution after discontinuation and subsequent benefit from aripiprazole." (PMID 41531626, 2025).
osteoarthritis (12 papers, 2012 to 2025). A noninflammatory degenerative joint disease occurring chiefly in older persons, characterized by degeneration of the articular cartilage, hypertrophy of bone at the margins and changes in the synovial membrane. "SOX5 has also been associated with cartilage and osteoarthritis in animal studies, but not in human cartilage." (PMID 35140737, 2021). "SOX5, one of the new signals, has been previously reported to be upregulated in human osteoarthritis cartilage and has been associated with back pain and with lumbar intervertebral disc degeneration." (PMID 34450027, 2021). "The dysregulation in the function of SoxD proteins (i.e. Sox5, Sox6, Sox13, and Sox23) have been implicated in different disease conditions such as chondrodysplasia, cancer, diabetes, hypertension, autoimmune diseases, osteoarthritis among others." (PMID 33230925, 2020). "Support for shared genetic influences on CBP and arthritis come from other recent work by our group: a genome-wide meta-analysis of CBP identified and replicated a variant in the gene SOX5, previously implicated in osteoarthritis, that was a significant predictor of CBP." (PMID 30301474, 2018). "CircSEC24A provides a potential target for the clinical diagnosis and treatment of Osteoarthritis (OA) through miR-142-5p/SOX5." (PMID 34905439, 2021). "To explore possible functions of SOX5 in RA pathogenesis, we firstly compared the levels of SOX5 expression between RA and osteoarthritis (OA) patients." (PMID 27550416, 2016). "Our data indicated SOX5 levels were higher in synovium and synovial fluid from RA compared to osteoarthritis patients." (PMID 27550416, 2016). "The results implied that MiR-194 and Sox5 were deregulated during osteoarthritis, and they are likely to be target for osteoarthritis therapy." (PMID 22396742, 2012). "What is more important, we found that MiR-194 was elevated in IL-1β induced osteoarthritis, and it is accompanied by decreased expression of Sox5." (PMID 22396742, 2012). "We found that miR-194 was up-regulated in the osteoarthritis group while Sox5 was down-regulated compared with control group." (PMID 22396742, 2012). "The down-regulation of miR-194 increases its direct targeting of gene Sox5, and results in enhanced chondrogenic differentiation of hASCs, what is more, we found that MiR-194 was up-regulated and Sox5 was down-regulated in osteoarthritis." (PMID 22396742, 2012). "Prior work indicates an important role for SOX5 in articular cartilage and osteoarthritis, and such a role was also supported by our functional annotation showing that rs12310519 (and SNPs in high LD) overlapped with potential regulatory regions for chondrogenic cells." (PMID 30261039, 2018). "We further asked whether the expression of miR-194 is in accordance with Sox5 in osteoarthritis, we treated primary chondrocyte with IL-1βfor 24 h and the total RNA and protein was collected for qRT-PCR and Western-blotting Assay." (PMID 22396742, 2012). "We also found that miR-194 correlates with Sox5 in osteoarthritis." (PMID 22396742, 2012). "We also found that miR-194 and Sox5 play a role in osteoarthritis." (PMID 22396742, 2012). "Although variants in SOX5 have not been reported in prior GWAS of limb osteoarthritis (knee, hip, or hand), the association of SOX5 with CBP may involve the spinal structures specifically." (PMID 30261039, 2018). "For clinical relevance, we extended our analysis to published data from knee synovial tissues of osteoarthritis patients, 28 29 which similarly showed that THY1-PRG4+CLIC5+ FLS exhibited SOX5, FOXO1 and CREB5 regulon activity." (PMID 36414376, 2023).